ZYX (zyxin)
Diseases named in the same sentence as ZYX in open-access papers (continued):
Sharing a sentence is not in itself a finding about the gene and the disease.
ZYX also shares sentences with these, for which no sentence is quoted: ovarian carcinoma (5 papers); oral squamous cell carcinoma (3); acute myelogenous leukemia (2); laryngeal carcinoma (2); Alzheimer disease (1); androgenetic alopecia (1); brain injury (1); cardiac diseases (1); cardiac hypertrophy (1); cholangiocarcinoma (1); clear cell renal cell carcinoma (1); diabetes mellitus (1); dyslipidemia (1); E. coli infection (1); endothelial dysfunction (1); glioma (1); injury (1); laryngeal squamous cell carcinoma (1); lipoma (1); liver cancer (1); Minimal Change Disease (1); Obesity (1); pancreatic cancer (1); primary immunodeficiency (1); Sepsis (1); stomach cancer (1); Thrombocytopenia (1); viral myocarditis (1).